SYNE3-AS1 (SYNE3 antisense RNA 1)
Synonyms: AL133467.1
Gene: Long non-coding RNA gene on chromosome 14 (95,516,116 to 95,517,913, forward strand). Ensembl gene ENSG00000258572.
Diseases named in the same sentence as SYNE3-AS1 in open-access papers:
SYNE3-AS1 is named in the same sentence as 4 diseases in open-access papers, as found by Europe PMC text mining. Sharing a sentence is not in itself a finding about the gene and the disease.
SYNE3-AS1 shares sentences with these, for which no sentence is quoted: breast carcinoma (1 paper); breast tumor (1); cancer (1); ovarian carcinoma (1).